LSM11 (LSM11, U7 small nuclear RNA associated)
Description:
Component of the U7 snRNP complex that is involved in the histone 3'-end pre-mRNA processing. Increases U7 snRNA levels but not histone 3'-end pre-mRNA processing activity, when overexpressed. Required for cell cycle progression from G1 to S phases (By similarity). Binds specifically to the Sm-binding site of U7 snRNA.
Synonyms: FLJ38273; AGS8
Tractability: Small molecule: a structure with a bound ligand is known. PROTAC: UniProt records ubiquitination sites on it; ubiquitination databases record sites on it; its protein half-life has been measured.
Gene: Protein-coding gene on chromosome 5 (157,743,712 to 157,760,709, forward strand). Ensembl gene ENSG00000155858.
Subcellular location: Nucleus
Subcellular location (Human Protein Atlas): Nucleoplasm; Nuclear bodies
Pathways (Reactome):
Metabolism of RNA: SLBP Dependent Processing of Replication-Dependent Histone Pre-mRNAs; SLBP independent Processing of Histone Pre-mRNAs
Gene expression (Transcription): RNA Polymerase II Transcription Termination
Gene Ontology:
Molecular function: protein binding; U7 snRNA binding; RNA binding
Biological process: mRNA 3'-end processing by stem-loop binding and cleavage; positive regulation of G1/S transition of mitotic cell cycle; regulation of chromatin organization; 7-methylguanosine cap hypermethylation; nuclear histone mRNA catabolic process
Cellular component: nuclear body; nucleoplasm; nucleus; telomerase holoenzyme complex; U7 snRNP; histone pre-mRNA 3'end processing complex
Genetic constraint (gnomAD): Loss-of-function variants: 14 observed, 23.54 expected, observed/expected ratio (o/e) 0.59, 90% interval 0.39 to 0.93. The synonymous counts are far from expectation, so gnomAD's model fits this gene poorly and the ratio says little. Missense variants: 493 observed, 408.88 expected, observed/expected ratio (o/e) 1.21, 90% interval 1.12 to 1.3. Synonymous variants: 207 observed, 164.5 expected, observed/expected ratio (o/e) 1.26, 90% interval 1.12 to 1.41.
Homologues: Orthologues: macaque LSM11 (98% identical), dog LSM11 (94% identical), pig LSM11 (94% identical), chimpanzee LSM11 (93% identical), mouse Lsm11 (89% identical), rat Lsm11 (89% identical), rabbit LSM11 (58% identical), guinea pig LSM11 (57% identical), tropical clawed frog lsm11 (44% identical), zebrafish lsm11 (42% identical), Drosophila melanogaster Lsm11 (21% identical), Caenorhabditis elegans C49H3.4 (11% identical).
Diseases named in the same sentence as LSM11 in open-access papers:
LSM11 is named in the same sentence as 14 diseases in open-access papers, as found by Europe PMC text mining. Sharing a sentence is not in itself a finding about the gene and the disease. The quoted sentences say what the papers report.
Aicardi–Goutières syndrome (3 papers, 2021 to 2023). "Misprocessing of canonical histone transcripts in a subset of Aicardi–Goutières syndrome (AGS) patients with biallelic mutations in LSM11 and RNU7-1 specifically disturbs linker histone stoichiometries and leads to type I IFN signatures by cGAS redistribution and activation within the nucleus." (PMID 35084490, 2022).
glioma (1 paper, 2021). A benign or malignant brain and spinal cord tumor that arises from glial cells (astrocytes, oligodendrocytes, ependymal cells). "Both LSM11 and SARNP played roles in preventing disorders of cell protein synthesis or cell division, and their decreased expression in gliomas may be associated with glioma development." (PMID 34482648, 2021). "LSM11 participated in histone RNA 3’ processing and SARNP, playing a role in mRNA splicing and export, was not only significant in glioma but also acted as an important molecule in triple‐negative breast cancer." (PMID 34482648, 2021).
myeloma (1 paper, 2023). "We repeated this experiment using a cytoplasmic extract from mouse myeloma cells rather than from Hela cells and an additional Lsm11 protein encompassing all 168 amino-terminal amino acids of the protein." (PMID 37562960, 2023). "Readily detectable binding of the methylosome to the Lsm10/11ΔL dimer was also observed in a cytoplasmic extract from mouse myeloma cells (lane 4) and was not abolished by additionally deleting the entire amino-terminal region of Lsm11 (lane 5)." (PMID 37562960, 2023).
osteoarthritis (1 paper, 2023). A noninflammatory degenerative joint disease occurring chiefly in older persons, characterized by degeneration of the articular cartilage, hypertrophy of bone at the margins and changes in the synovial membrane. "The inhibition of Lsm11 by silencing RNA (siRNA) reversed the increased ability of chondrogenesis by knocking out miR146a both in vivo and in vitro, suggesting that miR146a inhibits chondrogenesis by directly inhibiting Lsm11 in MSCs, which may be a novel target for treating osteoarthritis." (PMID 36939200, 2023).
cancer (1 paper, 2023). A tumor composed of atypical neoplastic, often pleomorphic cells that invade other tissues. "KANSL3 and LSM11 are novel targets as not much is previously published about them in regards to cancer." (PMID 37161535, 2023).
LSM11 also shares sentences with these, for which no sentence is quoted: adenoid cystic carcinoma (1 paper); breast carcinoma (1); colon cancer (1); esophageal carcinoma (1); lung adenocarcinoma (1); Lynch syndrome (1); ovarian carcinoma (1); stomach adenocarcinoma (1); uterine corpus endometrial carcinoma (1).